SPOCK2 (SPARC (osteonectin), cwcv and kazal like domains proteoglycan 2)
Description:
May participate in diverse steps of neurogenesis. Binds calcium.
Synonyms: KIAA0275; testican-2
Tractability: Antibody: UniProt places it where antibodies can reach, with high confidence; UniProt predicts a signal peptide or a membrane-spanning region; its Gene Ontology location is reachable by antibodies, with medium confidence. PROTAC: its protein half-life has been measured.
Gene: Protein-coding gene on chromosome 10 (72,059,034 to 72,089,032, reverse strand). Ensembl gene ENSG00000107742.
Subcellular location: Secreted, extracellular space, extracellular matrix
Gene Ontology:
Molecular function: calcium ion binding; protein binding; metalloendopeptidase inhibitor activity; extracellular matrix binding; glycosaminoglycan binding
Biological process: extracellular matrix organization; positive regulation of cell motility; regulation of cell differentiation; regulation of cell-substrate adhesion; synapse assembly
Cellular component: extracellular matrix; gel phase of interstitial matrix
Genetic constraint (gnomAD): Loss-of-function variants: 39 observed, 56.58 expected, observed/expected ratio (o/e) 0.69, 90% interval 0.53 to 0.9. The upper end of that interval is the gene's LOEUF score, 0.9, which puts it in group 3 of 6, group 1 being the genes least tolerant of losing a copy. Missense variants: 523 observed, 537.18 expected, observed/expected ratio (o/e) 0.97, 90% interval 0.9 to 1.05. Synonymous variants: 217 observed, 213.59 expected, observed/expected ratio (o/e) 1.02, 90% interval 0.91 to 1.14.
Homologues: Orthologues: chimpanzee SPOCK2 (99% identical), macaque SPOCK2 (98% identical), guinea pig SPOCK2 (96% identical), rabbit SPOCK2 (96% identical), dog SPOCK2 (96% identical), pig SPOCK2 (95% identical), mouse Spock2 (94% identical), rat Spock2 (92% identical), tropical clawed frog spock2 (82% identical), zebrafish spock2 (70% identical), Drosophila melanogaster Cow (29% identical), Caenorhabditis elegans test-1 (17% identical). Paralogues in human: SPOCK3 (47% identical), SPOCK1 (46% identical), KIAA1210 (11% identical).
Diseases named in the same sentence as SPOCK2 in open-access papers:
SPOCK2 is named in the same sentence as 46 diseases in open-access papers, as found by Europe PMC text mining. Sharing a sentence is not in itself a finding about the gene and the disease. The quoted sentences say what the papers report.
ovarian carcinoma (10 papers, 2014 to 2025). A malignant neoplasm originating from the surface ovarian epithelium. "High expression of the SPOCK2 gene in ovarian cancer is associated with a poorer prognosis and reduced overall survival." (PMID 41465326, 2025). "Currently, few functional studies have focused on SPOCK2, which showed that SPOCK2 was associated with lung adenocarcinoma, prostate cancer, ovarian cancer, and bronchopulmonary dysplasia." (PMID 38388415, 2024). "Expression levels of GJB2, S100A2 and SPOCK2 were increased in ovarian cancer and their upregulation was linked to poor prognosis of patients with ovarian cancer." (PMID 31794425, 2019). "Taken together, GJB2, S100A2 and SPOCK2 might be three key genes in mediating tumor stage progression of ovarian cancer and causing poor prognosis." (PMID 31794425, 2019). "Another study (Ren, Wang & Li, 2011) reported that absence of SPOCK2 expression caused by hypermethylation of the SPOCK2 gene, may be related to the development and progression of ovarian cancer." (PMID 31338255, 2019). "In this study, based on comprehensive expression analysis and survival analysis, three genes (GJB2, S100A2 and SPOCK2) were identified as key genes which may be associated with progression of ovarian cancer." (PMID 31794425, 2019). "Specifically, SPOCK2 promotes the invasion and migration of ovarian cancer cells, potentially through interactions with ITGA3 and the activation of FAK signaling, and is associated with a higher likelihood of metastasis." (PMID 41465326, 2025). "Specifically, SPOCK2 was highly expressed in ovarian cancer, and high level of SPOCK2 promoted migration and invasion of glioma cells, whereas more evidences suggested a tumor suppressor role for SPOCK2." (PMID 36629984, 2023). "It has been reported that the has-miR-363-3p-SPOCK2 axis is involved in regulating the cytoskeleton of actin cells and plays a regulatory role in the staging and progression of ovarian cancer." (PMID 37841281, 2023). "In recent studies, SPOCK2 has been shown to be highly expressed in ovarian cancer and lowly expressed in prostate cancer." (PMID 33244319, 2020). "SPARC (osteonectin), cwcv and kazal-like domains proteoglycan 2 (SPOCK2) is known as a secreted protein that is acidic and cysteine-rich, playing a significant role in the development and progression of ovarian cancer, endometrial cancer, and prostate cancer." (PMID 33244319, 2020). "Taken together, overexpressed lncRNAs/pseudogenes-mediated downregulation of hsa-miR-363-3p leads to increased expression of SPOCK2, modulating actin cytoskeleton and thereby resulting in progression of ovarian cancer." (PMID 31794425, 2019). "Among these miRNA-mRNA pairs, hsa-miR-363-3p-SPOCK2 axis was the most potential in suppressing progression of ovarian cancer." (PMID 31794425, 2019). "By combination of ceRNA mechanism and these analytic findings, the six pseudogenes were identified as the potential regulators of hsa-miR-363-3p-SPOCK2 axis in ovarian cancer." (PMID 31794425, 2019). "Altogether, hsa-miR-363-3p-SPOCK2 axis was considered as the potential pathway, involving in progression of ovarian cancer." (PMID 31794425, 2019). "For RFS of patients with ovarian cancer, SPOCK2 and FAXDC2 were unfavorable prognostic biomarkers but ADAMDEC1, CCNA2, FAM181A, FOXA2, LRRTM1, NEIL3 and XPR1 were favorable prognostic biomarkers." (PMID 31794425, 2019). "Altogether, hsa-miR-363-3p-SPOCK2 axis may be the most potential pathway in mediating tumor stage progression of ovarian cancer." (PMID 31794425, 2019). "All these reports together with our current analytic results of expression and survival analysis demonstrate that GJB2, S100A2 and SPOCK2 may be three key oncogenes in the progression of ovarian cancer." (PMID 31794425, 2019). "In summary, a series of integrated bioinformatics analyses suggest that hsa-miR-363-3p-SPOCK2 axis may play key roles in progression of ovarian cancer by regulating actin cytoskeleton." (PMID 31794425, 2019).
ovarian carcinoma (continued). "Moreover, 6 pseudogenes and 8 lncRNAs were identified to potentially inhibit hsa-miR-363-3p-SPOCK2 axis in ovarian cancer." (PMID 31794425, 2019). "The established pseudogene/lncRNA-hsa-miR-363-3p-SPOCK2 pathway shed novel insight into molecular mechanism of ovarian cancer progression and may provide effective therapeutic targets and promising prognostic biomarkers for ovarian cancer." (PMID 31794425, 2019). "Hence, hsa-miR-363-3p-SPOCK2 axis may suppress invasion and metastasis through regulation of actin cytoskeleton and finally block stage progression of ovarian cancer." (PMID 31794425, 2019). "Ovarian cancer patients with higher expression of GJB2, S100A2 and SPOCK2 showed better OS, which was identical with the analytic results obtained from TCGA cohort." (PMID 31794425, 2019). "Subsequently, we introduced the ovarian cancer data other than TCGA to further assess the survival effects of GJB2, S100A2, SPOCK2 and TGM1 on prognosis (OS) by Kaplan-Meier plotter." (PMID 31794425, 2019). "High expression of GJB2, S100A2, SPOCK2, TGM1or EPS8 indicated a poor OS of patients with ovarian cancer, whereas ovarian cancer patients with higher expression of ADAMDEC1, CHEK1, EGFL6, FAM181A, FOXA2, LYPD1, PART1 or XPR1 possessed better OS." (PMID 31794425, 2019).
prostate carcinoma (10 papers, 2008 to 2024). A carcinoma that arises from epithelial cells of the prostate gland. "The protein encoded by SPOCK2 is a component of the extracellular matrix, and down-regulation of SPOCK2 indicates a poorer prognosis for prostate cancer." (PMID 34030694, 2021). "In prostate cancer, in comparison to benign prostate hyperplasia, SPOCK2 was lower in cancer tissue samples." (PMID 37188984, 2023). "SPOCK2 expression was downregulated in prostate cancer and its overexpression suppressed prostate cancer cell invasion and migration." (PMID 36629984, 2023). "There were also 5 KLF5K369Q-downregulated and NTZ-upregulated genes whose lower expression levels in human prostate cancers were also significantly associated with worse overall survival, including TMPRSS2, CALB1, SPOCK2, COL4A4, and COL4A3." (PMID 36810084, 2023). "A recent study indicated that SPOCK2 has the capability to impede the invasion and migration of prostate cancer cells." (PMID 37188984, 2023). "In prostate cancer, SPOCK2 mRNA level was lower in contrast to benign prostate hyperplasia, and the upregulation of SPOCK2 in prostate cancer cell lines via transfection inhibited cell invasion and migration, in vitro." (PMID 37188984, 2023). "SPOCK2 was previously reported to inhibit cancer cell invasion and migration in prostate cancer." (PMID 33244319, 2020). "The combination of DPYS or NSE1 hypermethylation showed a sensitivity of 80%, specificity of 95% and accuracy of 95% and the combination of NSE1 or SPOCK2 hypermethylation showed a sensitivity of 80%, specificity of 95% and accuracy of 96% in differentiating prostate cancer from normal." (PMID 18446232, 2008). "It is known that secreted protein acidic and cysteine rich (osteonectin), cwcv and kazal-like domains proteoglycan 2 (SPOCK2) plays a significant role in the development and progression of several human cancers; however, the role of SPOCK2 in prostate cancer (PCa) remains unclear." (PMID 31338255, 2019). "Upregulation of SPOCK2 negatively regulated MMP2 gene expression, which in turn inhibited the invasion and metastasis of prostate cancer cells." (PMID 34987577, 2021). "Based on methylation in primary tumors compared to normal adjacent tissues, NKX2-5, CLSTN1, SPOCK2, SLC16A12, DPYS and NSE1 are candidate biomarkers for prostate cancer (methylation range 50%–85%)." (PMID 18446232, 2008). "Among epigenetic biomarkers, most reports indicate GSTP1 hypermethylation as the diagnostic marker for prostate cancer; however, NKX2-5, CLSTN1, SPOCK2, SLC16A12, DPYS, and NSE1 also have been reported to be regulated by methylation mechanisms in prostate cancer." (PMID 24213111, 2011). "Compared to adjacent normal prostate, all 8 genes had significantly higher methylation in prostate cancer by t-test analysis (P<0.001 for NKX2-5; P<0.001 for SPOCK2; P = 0.004 for GALR2; P<0.001 for CLSTN1; P<0.001 for NSE1; P<0.001 for DPYS; P = 0.019 for FOXN4; P<0.001 for SLC16A12)." (PMID 18446232, 2008).
endometrial cancer (8 papers, 2014 to 2025). Primary or metastatic malignant neoplasm involving the endometrium (mucous membrane that lines the endometrial cavity). "Upregulated SPOCK2 in endometrial cancer can suppress tumor cell invasion and migration by modulating MMP2 activation." (PMID 40375334, 2025). "SPOCK2 is a secreted protein that plays essential roles in OV carcinogenesis, endometrial cancer, PRAD, and LUAD." (PMID 38535087, 2024). "Regrading to SPOCK2, the group of Ren F confirmed that SPOCK2 contributed to the progression of endometrial cancer by modulating the biological behavior of cancer cells." (PMID 31794425, 2019). "Similarly, SPOCK2 expression was detected in normal endometrium, while its expression was decreased in endometrial cancer." (PMID 36629984, 2023). "For instance, SPOCK2 has been reported to contribute to endometrium cancer progression, in vitro." (PMID 37188984, 2023). "In addition, SPOCK2 upregulation impaired the ability of invasive and adherence, and increased apoptosis of endometrial cancer cells, its overexpression suppressed cell proliferation via impeding cell cycle progression." (PMID 36629984, 2023). "SPOCK2 regulates endometrial cancer cells by targeting MMP2." (PMID 35342412, 2022).
glioma (8 papers, 2019 to 2025). A benign or malignant brain and spinal cord tumor that arises from glial cells (astrocytes, oligodendrocytes, ependymal cells). "Low expression of CDKN2B and SPOCK2 was associated with poor survival in glioma patients in the TCGA LGG/GBM dataset." (PMID 36973285, 2023). "Moreover, in a glioma-related study, we founded that SPOCK2 could be associated with astrocytic activation." (PMID 38388415, 2024). "A heatmap was generated to illustrate the expression levels of SPOCK2 across numerous tumors, including glioma, kidney chromophobe (KICH), non-small cell lung carcinoma (NSCLC), and ovarian serous cystadenocarcinoma (OV)." (PMID 38535087, 2024). "The expression of YTHDF2 was negatively correlated with CDKN2B and SPOCK2 mRNAs in multiple pediatric glioma datasets, supporting the pathological role of YTHDF2 negatively regulating CDKN2B and SPOCK2 transcripts in glioma development." (PMID 36973285, 2023). "SPOCK2 abolishes the inactivation of MT-MMPs by other SPOCK family members, causing ECM remodeling and allowing the migration of glioma cells expressing MT1-MMP." (PMID 34203581, 2021). "Finally, we investigated the expression pattern of these risk genes within the TME of PACA and discovered that SPOCK2 was specifically and highly expressed in CD8TEX cells in numerous tumors, including BCC, glioma, KICH, LIHC, NSCLC, OV, PACA, PRAD, and SCC." (PMID 38535087, 2024). "Furthermore, studies have consistently reported reduced SPOCK2 expression in high‐grade gliomas." (PMID 40781854, 2025). "In contrast, high levels of SPOCK2 could abrogate this inhibition of MMP2 by SPOCK3 and increase the invasiveness of glioma cells." (PMID 31338255, 2019). "Following induction of NP by CCI, there was a significant increase in SPOCK2 expression specifically in astrocytes but not as pronounced in microglia, indicating its involvement in the mechanism of NP related to astrocyte activation, which is consistent with a study on glioma." (PMID 38388415, 2024).
breast cancer (7 papers, 2008 to 2024). A primary or metastatic malignant neoplasm involving the breast. "Another study further found that oligonucleotide polymorphism of the SPOCK2 gene was also related to the deletion of 16q chromosome in breast cancer, which was the first report to describe the correlation between the SPOCK2 gene and cancer." (PMID 31338255, 2019). "Moreover, we were able to show a strong association of SPOCK2 expression at the mRNA level in breast cancers with exclusive cerebral metastasis in an independent online cohort of 204 primary breast cancers." (PMID 34203581, 2021). "SPOCK2 and GJD3 mRNA overexpression were also found to be associated with cerebral metastasis in an external online database consisting of 204 primary breast cancers." (PMID 34203581, 2021). "SPOCK2 was significantly upregulated in breast cancer cells that metastasized to the brain." (PMID 34203581, 2021). "The overexpression of SPOCK2 mRNA in primary breast cancers that metastasized to the brain was further corroborated by data mining in a publicly available online dataset of 204 primary breast cancers (p = 0.0026)." (PMID 34203581, 2021). "In the current study, we found that the expression of BOC, SPOCK2, and GJD3 is upregulated in the ER- primary breast cancer samples of patients who developed brain metastases." (PMID 34203581, 2021). "Three genes BOC, SPOCK2, and GJD3 were overexpressed in the group of primary breast cancers which developed brain metastasis." (PMID 34203581, 2021). "Although Col13a1 and Spock2 mRNA abundance showed trends towards up- and downregulation respectively in mammary tumours with metastases, this was not significant and will need to be reassessed in a larger independent cohort." (PMID 37402051, 2023). "Finally, SLC16A12, GALR2, TOX, SPOCK2, EGFR5 and DPYS are candidate biomarkers for breast cancer (methylation range 33%–79%) with the combination of EGFR5 or TOX hypermethylation showing a sensitivity of 92% and specificity of 92%." (PMID 18446232, 2008).
colon cancer (5 papers, 2007 to 2023). "In colon cancer, the hypermethylation of SPOCK2 gene was higher in cancer cells than that in the normal mucosal tissue adjacent to the cancer." (PMID 37188984, 2023). "The relationship between colon cancer and SPOCK2 was further verified by Sambuudash, Kim & Cho (2017), whereby it was found that the incidence of SPOCK2 methylation in colon cancer was significantly higher than that in adjacent normal mucosa tissues." (PMID 31338255, 2019). "In situ hybridization analyses using C57BL/6 ApcMin/+ colon tumor samples also validated that Wif, Tesc, Spock2 and Casp6 were strongly expressed in dysplastic cells of the tumors (data not shown)." (PMID 17615082, 2007). "Among gastrointestinal malignancies, SPOCK2 expression was reported in colon cancer." (PMID 37188984, 2023). "In a panel of 20 colon cancer cases, all these genes except IRX5, TFAP2E and TFAP2C showed significantly higher methylation in cancer by t-test analysis (P<0.001 for NKX2-5, DPYS SPOCK2, GALR2 and SLC16A12; P = 0.008 for FOXN4)." (PMID 18446232, 2008). "SPOCK2 belongs to a group of SPARC proteins, which encompasses various proteins that have been studied in various gastrointestinal malignancies, such as biliary tract cancers (BTC), PDAC, and colon cancer." (PMID 37188984, 2023). "Similarly NKX2-5, SPOCK2, SLC16A12, DPYS and GALR2 are candidate biomarkers for colon cancer (methylation range 60%–95%) and GALR2 hypermethylation showed a sensitivity of 85% and specificity of 95%." (PMID 18446232, 2008).
bronchopulmonary dysplasia (4 papers, 2014 to 2024). Bronchopulmonary dysplasia is a chronic respiratory disease that results from complications related to lung injury during the treatment of infant acute respiratory distress syndrome in low-birth-weight premature infants or from abnormal lung development in older infants. "SPOCK2 was identified as bronchopulmonary dysplasia susceptibility gene and had important implications for lung development." (PMID 36629984, 2023). "SPOCK2 mRNA and protein are present in the lungs and are involved in alveolar development and bronchopulmonary dysplasia susceptibility." (PMID 33244319, 2020). "A recent study revealed a role for SPOCK2/Testican-2 in bronchopulmonary dysplasia and alveolarization, which suggests a possible link between this HSPG and the transitioning of AT2 into AT1 cells." (PMID 24690998, 2014).
viral infection (3 papers, 2020 to 2024). "SPOCK2 expression was shown to be associated with lung injury induced by viral infection and the mouse LRRK2 knockout model suggested that LRRK2 regulates innate immune responses and lung inflammation during Mtb infection." (PMID 37471455, 2023). "These included IFITM2 and IFITM3, IFIT family members which play a role in viral infection and SPOCK2, upregulated upon virus infection and recognized as protective against influenza infection." (PMID 39026668, 2024). "The SPARC/osteonectin, cwcv and kazal-like domains proteoglycan 2 (SPOCK2) is a complex type of secreted proteoglycan involved in forming a protective barrier against viral infection." (PMID 33244319, 2020). "It was reported that SPOCK2 can prevent viral infection in lung epithelial cells." (PMID 33244319, 2020). "We speculated that viral infection-induced SPOCK2 expression may also be the result of immune system activation." (PMID 33244319, 2020). "SPOCK2 is known to be expressed by T cells during anti-viral responses, but to our knowledge enhanced expression by ILCs during viral infection has not been documented previously." (PMID 39026668, 2024).
benign prostate hyperplasia (2 papers, 2019 to 2023). "The mRNA level of SPOCK2 was significantly lower in the PCa tissue compared to benign prostate hyperplasia." (PMID 31338255, 2019).